EGFR (epidermal growth factor receptor)
Diseases named in the same sentence as EGFR in open-access papers (continued):
Sharing a sentence is not in itself a finding about the gene and the disease.
tumor (continued). "Influence of anti‐EGFR treatment did not justify these findings in any case, because it was administered to patients after tumour sample collection." (PMID 37097008, 2023). "Circulating PRL levels in EGFR and HER2 transgenic mice were increased, and inhibiting EGFR or HER2 signaling with oral lapatinib suppressed circulating PRL by 72% and attenuated tumor PRL expression by 80%, and also attenuated downstream tumor EGFR/HER2 signaling." (PMID 37446128, 2023). "In contrast, a CLIA-certified drug sensitivity assay of an organoid culture derived from the patient’s tumor identified several therapeutic choices, including Bruton’s tyrosine kinase (BTK) inhibitor ibrutinib, as well as the EGFR inhibitors afatinib and erlotinib." (PMID 37202426, 2023). "Though having promising potential, representative EGFR inhibitor gefitinib has frequently induced chemo-resistance in many clinical studies, and thus it has failed to improve the survival rate in tumor patients." (PMID 36768961, 2023). "Thus, the AREG/EGFR/HIF-1α signaling pathway contributes to Th9 cell differentiation and anti-tumor function." (PMID 36154925, 2023). "The effect remained stable in the subgroup (n = 41) of tumor samples with available matched negative controls (EGFR and PTEN r = 0.246, p = 0.009, EGFR and p-mTOR r = −0.207, p = 0.207; p-mTOR and ER r = 0.226, p = 0.014)." (PMID 37623437, 2023). "Cooperation between EGFR and ECM receptor integrins promotes tumor progression and aggressiveness." (PMID 37498672, 2023). "According to the NCI Thesaurus13 definition, Gefitinib inhibits the catalytic activity of numerous tyrosine kinases, including the epidermal growth factor receptor (EGFR), which may result in inhibition of tyrosine kinase-dependent tumor growth." (PMID 37391722, 2023). "Our study found a significant relationship between VF recovery and low EGFR expression in tumor tissues, but not Ki67 expression." (PMID 36874088, 2023). "Furthermore, EGFR VIII was mostly amplified on eccDNA, making tumor cells more vulnerable to TKI treatment." (PMID 37337170, 2023). "Meanwhile, EGFR minicells loaded with siMDR1 reversed drug resistance in Caco-2/MDR1 tumor-bearing mice and MDA-MB-468/MDR1 tumor-bearing mice, leading to marked tumor inhibition, and improve the sensitive ability of these tumors with the MDR1 gene to chemotherapeutic drugs." (PMID 37896250, 2023). "Atezolizumab, has recently been approved by the EMA as monotherapy for the “first-line treatment of adult patients with metastatic NSCLC with PD-L1 expression ≥ 50% TC or ≥ 10% tumour-infiltrating IC and who do not have EGFR mutant or ALK-positive”." (PMID 36647072, 2023). "These include the combination of BRAF inhibitors with MEK inhibitors to block multiple signaling pathways, the use of EGFR inhibitors in combination with BRAF inhibitors, and the combination of targeted therapies with immunotherapy to enhance the immune response against tumor cells." (PMID 37444584, 2023). "Notably, alongside HER2, both EGFR and HER3 expression have been identified in numerous FMC cell lines and tumor samples." (PMID 37835664, 2023). "Taken together, our results demonstrate that pharmacological co-targeting of EGFR and MTOR using clinically available drugs represents an effective treatment paradigm for EGFR-driven GBMs, acting both by inhibiting tumor cell growth and modulating the immune tumor microenvironment." (PMID 36831214, 2023).
tumor (continued). "Although EGFR functions in tumor processing and is a common therapeutic target, it was not proven to be a prognostic biomarker for recurrence in early-stage LUAD with R0 resection in our meta-analysis." (PMID 37907475, 2023). "Interestingly, the present evidence suggests that PARP or EGFR blockade affects the enrichment and relative proportion of ALDH+ cells among tumour cells." (PMID 37441599, 2023). "Determining the tumor KRAS status in a patient with stage IV CRC is important, because KRAS-mutant CRC is resistant to EGFR monoclonal antibodies (mAbs) as the mutant RAS continues the activation of the MAPK pathway downstream of EGFR-RAS." (PMID 38139338, 2023). "Moreover, immunohistochemical staining of the tumor tissue was performed, compared with the control group, the expressions of Ki-67, MMP9, and EGFR in the myricetin treatment group were significantly decreased." (PMID 38026996, 2023). "Moreover, the expression of both JWA and NEDD4L was increased; however, EGFR, p-EGFR, p-AKT, and p-STAT3 expression levels were reduced in JAC4-treated tumor tissues compared to those in the control group." (PMID 37240137, 2023). "EGFR-CAR T cells, which secrete PD-1 scFv, could kill tumor cells in a gastric cancer model for a long time." (PMID 36341440, 2022). "The RTK epidermal growth factor receptor (EGFR) activates AKT that directly phosphorylates β-catenin on Ser552, which increases the cytosolic and nuclear β-catenin levels and transcriptional regulation, thereby promoting tumor cell invasion." (PMID 35359365, 2022). "Previous evidence has shown that EGFR-TKIs could diminish VEGF expression and inhibit tumor angiogenesis; when combined with antiangiogenic agents, they facilitate substantial survival benefits in advanced NSCLC patients." (PMID 36031613, 2022). "The first is that SpTR can reduce the residual tumour burdens, which are required to generate an effective immune response in immunotherapies such as CAR-T therapies, HSPPC-96 vaccination and rindopepimut (a peptide vaccine against EGFR-vIII-expressing GBMs)." (PMID 35664765, 2022). "Finally, we show that GZ17-6.02 downregulates several GSC super-enhancer genes, which are key to EGFR signaling and GSC proliferation, and demonstrate that GZ17-6.02 suppresses tumor growth in a subcutaneous tumor model." (PMID 35456993, 2022). "For NSCLC, activation of EGFR, ALK, ROS-1, and other targetable genes in the tumor are evaluated." (PMID 35806042, 2022). "If EGFR or CK5/6 was positive, then it was considered a basal-like tumor." (PMID 36153494, 2022). "Overall, DHRS7 expression was higher in non-tumor samples compared to tumor samples and, accordingly, EGFR expression was higher in tumor samples compared to non-tumor prostate samples." (PMID 35804847, 2022). "Although serum tumor markers and CT features can assess EGFR mutation status in NSCLC, the accuracy of predicting EGFR mutations by these two methods alone is not sufficient." (PMID 35422977, 2022). "In addition, HGF, MET amplification, and EGFR T790M lead to the upregulation of PD-L1 expression in NSCLC and promote immune escape by tumor cells through different mechanisms mediated by the PI3K-Akt, MAPK, and NF-κB pathways." (PMID 35840984, 2022). "Although anti-EGFR/PD-L1 BsAbs were equally potent in suppressing tumor growth as corresponding mAbs, no significant tumor difference in growth inhibition was observed between anti-EGFR/PD-L1 BsAbs and corresponding mAbs." (PMID 35890277, 2022). "It is possible that for these three EGFR TKIs differences in pharmacokinetic and pharmacodynamic properties known at a therapeutic level are not appropriate to explain the differences in tumor-to-lung contrast and PET image quality." (PMID 35453931, 2022).
tumor (continued). "Although inactivation of Rbm10, Rb1, or Apc did have similar effects on EGFR and KRAS mutant tumor growth, Serine/threonine kinase 11 (Stk11, also known as Lkb1) and SET domain containing 2, histone lysine methyltransferase (Setd2) inactivation had opposite effects in the two oncogenic settings." (PMID 35252550, 2022). "In the subgroup analyses in the EGFR wild type population, the presence of GAS5 SNP rs145204276 Ins/Del + Del/Del may be correlated with an advanced tumor stage (p = 0.014) and distal metastases (p = 0.020) in non-smoker individuals." (PMID 36011604, 2022). "Copper also could trigger the expression of GPER, VEGF, and HIF-1α via activating EGFR/ERK/c-fos transduction pathway, affecting the angiogenesis and tumor progression in BRCA and LIHC." (PMID 36052076, 2022). "This ADC is specific to EGFR expressing cells, is only cytotoxic in these cells in vitro and showed anti-tumour activity in vivo, but it is still not tested in clinical trials." (PMID 35892707, 2022). "One of the oncogenes on 7p is Epidermal Growth Factor Receptor (EGFR), which is amplified in about one-third of GBMs, and in 10q there is the inactivation of tumor-suppressor genes in the telomeric region of 10q, especially Phosphatase and Tensin Homolog (PTEN)." (PMID 35804976, 2022). "In the context of HNSCC, we previously reviewed how the combined use cetuximab, as an anti-EGFR ADCC-inducing antibody, with NK cell targeting immunotherapies could control tumor outgrowth and restore immune-mediated antitumor function." (PMID 36268020, 2022). "Additionally, the blood and major organs were collected from both ‘control’ and ‘EGFR siRNA/PEG-SSNs’ groups for biochemical and histological analysis after 26 days of tumour inoculation." (PMID 36412852, 2022). "In preclinical models, targeted medicines aimed against EGFR, such as cetuximab and panitumumab, and those directed against VEGF, such as bevacizumab, have been demonstrated to generate a more immunogenic tumor profile, and so could be useful adjuncts to CRC." (PMID 35205254, 2022). "Hence, KSTAR predictions of EGFR and ERBB2 basal activity correspond with lapatinib response, including the surprising result of a HER2-negative tumor responding to HER2-specific therapy." (PMID 35879309, 2022). "Our study demonstrates that CXCL10, a representative inflamed immune-response cytokine, activates CXCR3 in tumor cells to induce the phosphorylation of Src and the NF-κB subunit, p65, and the expression of HIF1-α in persistent EGFR-mutant tumor cells during EGFR-TKI treatment." (PMID 36612121, 2022). "HSPB1, EGFR, and TYK2 were highly expressed in tumor tissue in the Human Protein Atlas database." (PMID 36171217, 2022). "Patients with recurrent disease who displayed favorable responses to EGFR TKI treatment may partly be explained by their small disease burden and low tumor heterogeneity." (PMID 35140316, 2022). "We also checked for the possible EGFR T790M mutation during TKI resistance, and no change in mutation level was detected in either the subcutaneous tumor model or in drug-resistant cells." (PMID 35319011, 2022). "The authors demonstrated that, with EGFR-targeting and macropinocytosis-intensifying bifunctional attributes, Fv-LDP-D3 has shown the remarkable potential of tumor imaging and prominent tumor inhibition in AsPC-1 (human pancreatic cancer cells with a homozygous KRASG12D mutation)-derived xenografts." (PMID 35154489, 2022). "In a drug screening study using ovalbumin-specific systems, EGFR TKI, especially afatinib, could enhance the efficacy of anti-PD-1 by improving MHC expression and decreasing PD-L1 expression in tumor cells." (PMID 36443704, 2022).
tumor (continued). "It has been reported that EGFR/MET may be involved in resistance of RTKs target therapy, and MET amplification is important in tumor metastasis." (PMID 35428350, 2022). "Effectively preventing and treating skin toxicity without damaging the anti-tumor efficacy of EGFR inhibitors is the ultimate goal we want to achieve." (PMID 35223483, 2022). "No targetable driver mutations (epidermal growth factor receptor [EGFR], anaplastic lymphoma kinase [ALK] and ROS‐1) and a programmed death‐ligand‐1 (PD‐L1) tumour proportion score of 25%–49% were shown." (PMID 35822082, 2022). "This “hijacking” of pro-tumor-immune cells is mediated immunologically by interleukins (IL) such as IL-6, platelet-derived growth factors, notch-signaling pathways, vascular endothelial growth factor (VEGF), or epidermal growth factor (EGFR)." (PMID 34687436, 2022). "Furthermore, this suggests that EGFR plays a crucial part in the progression of HCC, as its expression is correlated with a high rate of proliferation, an advanced tumor stage, intrahepatic metastasis, and poor disease-free survival." (PMID 36671388, 2022). "SIAHHigh/ON in TNBC residual tumors reflects that the EGFR/K-RAS/MAPK/SIAH pathway is ON, which indicates chemo-resistance, ineffective NACT/NST, and/or the need for additional adjuvant therapies to prevent progressive disease and early tumor relapse." (PMID 36176751, 2022). "It has been reported that 14 of 48 primary UMs and 3 of 14 UM cell lines over-expressed EGFR and that EGFR over-expressing tumours, but not EGFR negative tumours, showed an activated EGF-signature." (PMID 35781872, 2022). "The bsAb AFM24 developed by Affimed targets EGFR and CD16A located on innate immune cells and can bind and redirect innate immune cells such as NK cells and macrophages to EGFR+ tumor cells, thereby directly killing tumor cells." (PMID 36341333, 2022). "Moreover, five pathological pathways, including the PI3K/AKT/FGFR/MAPK signaling, EGFR-related signaling, AMPA-related signaling, Notch signaling and Wnt signaling pathways, had a high correlation with tumor development." (PMID 35654793, 2022). "This PBPK model without EGFR was not able to capture the right tumor-to-lung contrast for mainly afatinib (PE 44% to −62%)." (PMID 35890095, 2022). "With surface modification by the epidermal growth factor receptor targeting peptide GE11, the prepared nanoparticles could efficiently accumulate in tumor tissue and significantly inhibit tumor growth." (PMID 35845404, 2022). "It has been reported that EGFR and Notch signaling pathways are the most unbalanced in GBM cell lines, the former because of its hyper-activation in several tumor cells, and the latter due to its effects on tumor progression." (PMID 35565451, 2022). "The results showed that all prognostic CRGs were elevated in advanced LUAD samples as well as in LUAD samples with brain metastases; in particular, EGFR was more expressed in samples with brain metastases, while PTGES3 was significantly elevated in all tumor samples used." (PMID 36060936, 2022). "Tumor samples of 248 patients with epidermal growth factor receptor (EGFR)/anaplastic lymphoma kinase (ALK)-negative non-squamous NSCLC treated with anti-PD-1 were molecularly tested by targeted next-generation sequencing or whole exome sequencing." (PMID 35592856, 2022). "EGFR-BiTE-ICOVIR-15K was able to replicate and lyse tumor cells in vitro." (PMID 36451817, 2022). "Taken together, EGFR mediates radiation response in HNSCC either directly, by regulating its own downstream activation partners or DNA damage response proteins, or indirectly, by initiating and regulating tumor-specific survival mechanisms." (PMID 35409179, 2022).
tumor (continued). "Atezolizumab has just received approval for the first-line therapy of adult patients with metastatic non-squamous NSCLC who do not have EGFR or ALK genetic tumour abnormalities." (PMID 36620544, 2022). "The anti-EGFR or anti-FAP bispecific antibody-targeted liposomal irinotecan (BS−LipoIRI) were examined for both in vitro and in vivo specific targeting ability and tumor growth inhibition effect." (PMID 35745775, 2022). "In particular, Avns inhibit tumor growth, migration, EMT and anoikis induced by EGFR activation." (PMID 35955669, 2022). "For example, NSCLC patients with EGFR mutation showed an unfavorable response to PD-L1/PD-1 inhibitors compared to those with wild-type EGFR, which could be related to the low TMB of EGFR-mutant tumor and an immunosuppressive TME." (PMID 36074553, 2022). "The solo treatment of EGFR inhibitors is probably not sufficient to suppress tumor growth, calling for alternative therapy to solve drug resistance." (PMID 35399718, 2022). "EGFR R521K harboring FaDu xenografts did not shrink, but the tumor growth was efficiently inhibited." (PMID 35626010, 2022). "The significance of EGFR staining is questionable, as it has been shown that EGFR expression as determined by immunohistochemistry is not the sole reflection of tumor biology." (PMID 34531264, 2022). "Among tumor cells, the luminal cell was positive for CK7 (3/3,100%) and CK 8/18 (5/5, 100%), and the myoepithelial-basal cell showed positivity for P63 (8/9, 89%), CK5/6 (9/9, 100%), EGFR 8 (5/5, 100%), and S100 (4/6, 67%)." (PMID 35966872, 2022). "In addition, miR-7 mimic-induced expression was shown to decrease the expression of EGFR, IGF-1R, and CRAF, which are regularly overexpressed in VemR cells and decreased tumor growth." (PMID 36012357, 2022). "The EGFR-targeting nanosystem was specifically bound to A431 tumor cells and promoted tumor destruction by laser activation without generating significant morphological damage to normal tissues." (PMID 35563645, 2022). "We plated hinge variant EGFR sdCAR-T cells and fluorescently labelled SKOV3 tumor cells with or without the addition of unmodified healthy donor HDFs (effector:target:HDF ratio of 1:1 or 1:1:1 respectively)." (PMID 35935988, 2022). "Additionally, EGFR, Mucin-1 (MUC1), and integrin beta-4 (ITGB4), which promote tumor growth and metastasis, are poor prognostic factors for this tumor." (PMID 36407096, 2022). "For example, several studies have shown that the anti-epidermal growth factor receptor (anti-EGFR; Cetuximab), used for the treatment of RAS wild-type mCRC, can mediate ADCC in vitro in an EGFR-dependent concentration, and more impressively, independently of the RAS status of the tumor." (PMID 35269922, 2022). "EGFR activation in human carcinoma cell lines increases matrix metalloproteinase-9 (MMP-9) activity, which increases cell invasion by facilitating the disintegration of ECM barriers for tumor invasion." (PMID 36081848, 2022). "This suggests that excessive tumor-generated HB-EGF might prevent PEPDG278D from binding to EGFR, and also suggests that EGFR signaling remains important to the tumors carrying activating mutations of KRAS, BRAF and/or PIK3CA." (PMID 35650607, 2022). "By comparing the ability of CD20 and EGFR CAR T cells to increase intracellular Ca2+ (Ca2+)i during interaction with their respective targets - B lymphoma and tumor pancreatic cell lines - we reported that EGFR CAR T cells presented fewer responses than CD20 CAR T cells." (PMID 36189315, 2022). "Cells were sorted into p75+/EGFR- SCs and p75+/EGFR+ SCP-like tumor-initiating cells." (PMID 35311647, 2022). "In EGFR-mutant NSCLC, tumor microenvironment (TME) tends to be a poorly immunogenic “immune desert” phenotype, and thus, it could be speculated that blocking PD-1/PD-L1 would enhance tumor growth and lead to resistance to ICIs, even HPD." (PMID 35990690, 2022).